POU2AF1 (POU class 2 homeobox associating factor 1)
Description:
Transcriptional coactivator that specifically associates with either POU2F1/OCT1 or POU2F2/OCT2. It boosts the POU2F1/OCT1 mediated promoter activity and to a lesser extent, that of POU2F2/OCT2. It recognizes the POU domains of POU2F1/OCT1 and POU2F2/OCT2. It is essential for the response of B-cells to antigens and required for the formation of germinal centers. Regulates IL6 expression in B cells as POU2F2/OCT2 coactivator (By similarity).
Synonyms: BOB1; OBF1; OCA-B; OBF-1; OCAB
Tractability: PROTAC: UniProt records ubiquitination sites on it; ubiquitination databases record sites on it.
Gene: Protein-coding gene on chromosome 11 (111,352,255 to 111,455,630, reverse strand). Ensembl gene ENSG00000110777.
Subcellular location: Nucleus
Gene Ontology:
Molecular function: protein binding; transcription coactivator activity; transcription coregulator activity; DNA binding; POU domain binding
Biological process: positive regulation of transcription by RNA polymerase II; cellular response to virus; germinal center B cell differentiation; humoral immune response; positive regulation of interleukin-6 production
Cellular component: RNA polymerase II transcription regulator complex; nucleus
Genetic constraint (gnomAD): Loss-of-function variants: 12 observed, 26.76 expected, observed/expected ratio (o/e) 0.45, 90% interval 0.29 to 0.73. The upper end of that interval is the gene's LOEUF score, 0.73, which puts it in group 2 of 6, group 1 being the genes least tolerant of losing a copy. Missense variants: 297 observed, 338.13 expected, observed/expected ratio (o/e) 0.88, 90% interval 0.8 to 0.97. Synonymous variants: 175 observed, 151.71 expected, observed/expected ratio (o/e) 1.15, 90% interval 1.02 to 1.31.
Gene-disease validity (ClinGen):
ClinGen rates the evidence that POU2AF1 causes each of these diseases.
agammaglobulinemia (autosomal recessive): Limited. A decreased level of serum immunoglobulins.
Cancer hallmarks: proliferative signalling (promotes)
Homologues: Orthologues: chimpanzee POU2AF1 (98% identical), macaque POU2AF1 (98% identical), dog POU2AF1 (91% identical), guinea pig POU2AF1 (90% identical), mouse Pou2af1 (89% identical), pig POU2AF1 (89% identical), rat Pou2af1 (87% identical), rabbit POU2AF1 (75% identical), tropical clawed frog pou2af1 (52% identical), Drosophila melanogaster CG11350 (22% identical), Drosophila melanogaster CG31626 (20% identical), Drosophila melanogaster CG32603 (18% identical).